BRCA1 (BRCA1 DNA repair associated)
Diseases named in the same sentence as BRCA1 in open-access papers (continued):
Sharing a sentence is not in itself a finding about the gene and the disease.
prostate carcinoma (continued). "BRCA1 and BRCA2 are genes centrally involved in this process, and mutations resulting in damaged BRCA1 or BRCA2 proteins can lead to various types of cancer such as breast, ovarian, or prostate cancer among the most closely associated." (PMID 30103829, 2018). "Extending the use of PARP inhibitors, beyond tumors with defective BRCA1/2, ATM, CHEK2, Fanconi's Anemia genes is of great interest, expecially in prostate cancer, where mutations in DNA repair genes are rare." (PMID 28415632, 2017). "We have previously demonstrated high BRCA1 levels in prostate cancer in comparison to normal prostate tissue." (PMID 28706506, 2017). "For example, prostate cancer risk by age 80 years at the 5th and 95th percentiles of the PRS varies from 7% to 26% for carriers of BRCA1 mutations and from 19% to 61% for carriers of BRCA2 mutations, respectively." (PMID 28448241, 2017). "Men below the age of 65 carrying a germline mutation in BRCA1 or BRCA2 have a 3.4-fold and 8.6-fold, respectively, risk to develop prostate cancer, which make BRCA2 mutations the strongest known genetic risk factor for prostate cancer." (PMID 28676659, 2017). "Over the past decade, convincing evidence has emerged regarding the role of PARP inhibitors in BRCA1/2 mutant cancers including ovarian, breast and prostate cancers." (PMID 28829366, 2017). "We have recently evaluated the contribution of the germline BRCA1/BRCA2 founder mutations for early-onset and/or familial prostate cancer in Portugal." (PMID 27532258, 2016). "Mutations in BRCA1, BRCA2, BRIP1/FANCCJ, CHEK2, MMR, and NBS1 have been found to confer an increased risk of prostate cancer." (PMID 26433958, 2015). "There was an approximately equal division of men between BRCA1 mutation carriers, BRCA2 mutation carriers and controls; 21 men had prostate cancer." (PMID 24489760, 2014). "The results from the Breast Cancer Linkage Consortium (BCLC) showed a RR of 4.65 of prostate cancer in male BRCA2 mutation carriers (RR 7.33 below the age of 65 years) and 1.07 in BRCA1 carriers (with a RR of 1.82 for men under 65 years old)." (PMID 25047061, 2014). "Familial mutations in one copy of either the BRCA1 or BRCA2 gene predispose patients to female breast (85% lifetime risk), ovarian (10% to 40%), male breast, pancreatic, or prostate cancer." (PMID 25093514, 2014). "The novel finding that prostate cancer cells with disparate radiosensitivity exhibit opposing regulation of BRCA1 following RT supports its involvement in determining radiation response." (PMID 25369795, 2014). "Early clinical phase 1 trials were conducted on breast, ovarian and prostate cancer targeting the BRCA1/2 muations." (PMID 24289880, 2013). "Knowledge of these mechanisms would provide a framework for the development of new therapeutic agents capable of manipulating BRCA1 splicing and treating BRCA1-related cancers (eg. breast ovarian and prostate cancer)." (PMID 22615956, 2012). "Beclin 1 is mapped to a region approximately 150 kb to BRCA1 on chromosome 17q21, which is usually deleted in breast, ovarian and prostate cancer." (PMID 20230646, 2010). "The PARP inhibitor olaparib was recently evaluated in a phase I clinical trial and showed antitumour activity in BRCA1 or BRCA2 mutation carriers with ovarian, breast or prostate cancer." (PMID 19904273, 2009). "We observed that men with prostate cancer and a BRCA2 mutation experienced relatively poor survival, in comparison to men with prostate cancer and a BRCA1 mutation." (PMID 18577985, 2008).
prostate carcinoma (continued). "Despite these numerous limitations, we believe that the differences observed in survival of the BRCA1 and BRCA2 carriers can be attributed to the adverse effect of the BRCA2 mutation on prostate cancer survival." (PMID 18577985, 2008). "In this study, we examined survival for men with prostate cancer and a BRCA2 mutation, and compared this to a similar group of men with a BRCA1 mutation." (PMID 18577985, 2008). "Time course studies of prostate cancer cell lines showed a delay in the induction of BRCA2 by I3C (first observed at 6 h) relative to that of BRCA1 (1 h)." (PMID 16434996, 2006). "The risk of prostate cancer is known to be elevated in carriers of germline mutations in BRCA2, and possibly also in carriers of BRCA1 and CHEK2 mutations." (PMID 15280931, 2004). "There was a significant difference in the incidence of the BRCA1 and BRCA2 mutations in the breast and prostate cancer cases (P = 0.05, two-tailed Fisher's exact test)." (PMID 9743298, 1998). "Although further studies and accumulating cases are required, these results suggest that recommendations for early screening for prostate cancer might need to be reconsidered for BRCA1 carriers." (PMID 41423785, 2026). "In this study, BRCA1 carriers were significantly associated with aggressive prostate cancer, and each category tended to be worse than noncarriers, suggesting a similar trend to BRCA2 carriers." (PMID 41423785, 2026). "According to the ESMO guidelines for screening and early detection, early PSA testing (baseline PSA followed by risk-adaptedfollow-up) can be offered to men >50 years, men >45 years with a family history of prostate cancer, African Americans >45 years, and BRCA1/2 carriers >40 years." (PMID 41590381, 2026). "We observed that BRCA1 pathogenic variants affect prostate cancer aggressiveness such as BRCA2 pathogenic variants, and the first case of aggressive prostate cancer with a BRCA1 pathogenic variant had long-term survival through early detection and multidisciplinary treatment." (PMID 41423785, 2026). "Moreover, we observed the first case of BRCA1-related aggressive prostate cancer showing long-term survival through early detection and multidisciplinary treatment." (PMID 41423785, 2026). "Unlike ovarian, breast, pancreatic, and prostate cancer, melanoma has a much lower frequency of BRCA1 and BRCA2 mutations, and there is little evidence of its contribution to melanoma pathogenesis." (PMID 40842586, 2025). "In summary, our investigation supports a role for BRCA2 and HOXB13 mutations in prostate cancer predisposition and provides reassurance that BRCA1, RNASEL, and ELAC2 are not substantially contributory in this cohort." (PMID 40433050, 2025). "In prostate cancer, the population without pathogenic variants in BRCA1/2, CHEK2, ATM and HOXB13E accounted for 98.0% of individuals and 95.8% of cases." (PMID 40016794, 2025). "Given the far more convincing association of prostate cancer with both somatic and gATM PVs in metastatic disease among 18/263 (6.8% germline 1.9%), even this 1 BRCA1 PV appears unlikely to be a driver in that tumour." (PMID 40046829, 2025). "Notably, CNVs deletions involving BRCA1 exon 22 and BRCA2 exon 27 have been shown to impair homologous recombination repair, playing a significant pathogenic role in advanced prostate cancer." (PMID 40725150, 2025). "There were 5271 prostate cancer patients included with 18 (0.3%) having germline BRCA1 alterations, 139 (2.6%) with BRCA2 alterations, 49 (0.9%) with germline ATM alterations, 15 (0.3%) with germline PALB2 alterations, and 27 (0.5%) with germline CHEK2 alterations." (PMID 40361359, 2025). "Mutations in the BRCA1 (breast and ovarian cancer susceptibility protein 1) and BRCA2 genes, which are associated with an increased risk of breast, ovarian, pancreatic, and prostate cancers, can cause Fanconi anemia and are linked to R-loop stabilization." (PMID 40271193, 2025).
prostate carcinoma (continued). "Moreover, our findings reinforce the importance of applying established pre-analytical best practices—already validated in other tumour types—to BRCA1/2 testing in prostate cancer." (PMID 40427202, 2025). "Co‐administration of HDAC and PARP inhibitors can synergistically reduce BRCA1 expression in prostate cancer or induce DNA damage in Ewing sarcoma models, such studies have focused on synthetic lethality and cell cycle arrest, with limited attention to immune modulation." (PMID 40789065, 2025). "Contributions of molecular diagnostics and next-generation sequencing being a new era of prostate cancer testing for Novel genetic biomarkers, like BRCA1/2, HOXB13, ATM, CHEK2, and DNA mismatch repair (MMR) genes, provide insight into inherited risk, disease progression, and targeted therapies." (PMID 40433050, 2025). "BRCA1 and BRCA2 are associated with advanced prostate cancer progression and poor prognosis." (PMID 40725150, 2025). "Furthermore, mutations in DNA damage repair genes such as BRCA2, ATM, CHEK2, BRCA1, RAD51, and PALB2 have been implicated in familial prostate cancer." (PMID 40716035, 2025). "Consequently, many HR deficient cases are identified by sequencing BRCA1/2 or PALB2, and this approach has led to initial approval of PARP inhibitors in multiple tumor types including breast, ovarian, pancreatic, and prostate cancer." (PMID 38589664, 2024). "Male BRCA2 mutation carriers are recommended to undergo prostate cancer surveillance through measuring PSA, digital rectal exams, and prostate USG over 40 years of age, and this could also be considered for BRCA1 mutation carriers." (PMID 39590130, 2024). "In human breast tumors, this phytochemical enhances the expression of the BRCA1 gene through H3 acetylation and AhR signal regulation, and in prostate cancer, it has been previously reported that resveratrol promotes tumor cell apoptosis by the deacetylation of FOXO." (PMID 39858410, 2024). "For those with BRCA1 PVs, it is advised to consider prostate cancer screening as well." (PMID 38339330, 2024). "Somatic BRCA1/2 mutations occur at some frequency in sporadic ovarian and prostate cancers; however, they are not necessarily accompanied by the inactivation of the remaining allele, and, hence, sensitivity to PARPis." (PMID 38612902, 2024). "In conclusion, this unicentric analysis of BRCA1/2 and HRR gene mutations in prostate cancer, analyzed over a 5-year period, found a lower prevalence of BRCA2 mutations than previously reported: only 4.9% are deemed eligible for olaparib treatment as per EMA approval." (PMID 39172235, 2024). "Interestingly, several teams report different clinical cases involving breast, ovarian, pancreatic, and prostate cancers, highlighting that PARPi resistance mechanisms would be shared between cancers of the BRCA1/2 spectrum." (PMID 38544832, 2024). "In several tumor types, particularly breast, ovarian, pancreatic, and prostate cancers, a strong correlation was observed between increased gLOH and biallelic alterations in other HR genes beyond BRCA1 and BRCA2, including BARD1, PALB2, FANCC, RAD51C, and RAD51D." (PMID 37761329, 2023). "In the BRCA1- and BRCA2-associated hereditary cancer syndromes, there is a higher risk of prostate cancer and gastrointestinal cancers (pancreatic, gastric, biliary tract, esophageal), while the risk of melanoma, colorectal, and lung cancer is still a matter for debate." (PMID 37239385, 2023). "Our findings may inform the use of PARP inhibitors beyond BRCA1/2-deficient tumors and support reevaluation of current biomarkers for PARP inhibition in prostate cancer." (PMID 36650183, 2023).
prostate carcinoma (continued). "For men, BRCA1/2 mutation carriers face a higher risk of developing BC in comparison to the general population, while BRCA2 mutation carriers have an increased risk of developing prostate cancer." (PMID 38203374, 2023). "The distribution of these variants (BRCA1 vs. BRCA2) in Ashkenazi men with prostate cancer is not clear." (PMID 36612302, 2023). "Finally, germline PVs in BRCA1, BRCA2, PALB2 or ATM were independently associated with short time to castration in patients with advanced prostate cancer." (PMID 37511593, 2023). "Because both 22RV1 and LNCaP cells harbor inactivating mutations in BRCA1/2 genes, we next examined whether MALAT1 can modulate the HR pathway in HR-proficient prostate cancer cells." (PMID 37812088, 2023). "In men with BRCA1 and 2 mutations in aggressive prostate cancer, the role of HPC sub-genes plays an important role, and BRCA2 mutations are associated with an increased incidence of prostate cancer." (PMID 37298192, 2023). "Mutations in the BRCA1 and BRCA2 genes increase the risk of developing prostate cancer." (PMID 36902416, 2023). "It is recommended to perform NGS-based BRCA1/2 somatic and germline testing when evaluating advanced prostate cancer patients to identify potential familial cancers and to utilize PARP inhibitors or platinum-based chemotherapies when the disease progresses to mCRPC." (PMID 37568814, 2023). "In addition to elevated cancer risk, germline BRCA1 or BRCA2 mutations in breast, ovarian and prostate cancer, predict both a better prognosis and superior response to cisplatin-based chemotherapy." (PMID 37020472, 2023). "Overall, these findings suggest that ivermectin could block NHEJ repair by targeting Ku70/Ku80 and HR repair by downregulating the expression of BRCA1 and Rad51, thereby triggering synthetic lethality in AR-positive prostate cancer cells." (PMID 36050295, 2022). "The seemingly elevated prostate cancer risk for BRCA1 P/LPV carriers was not confirmed in a recent family-based cohort that was published after the updated versions of the reviewed guidelines." (PMID 36230512, 2022). "Our previous findings suggested the joint effects of PRS and BRCA1 and BRCA2 pathogenic variants may identify men at clinically meaningful breast and prostate cancer risk levels." (PMID 34320204, 2022). "However, currently, the National Comprehensive Cancer Network (NCCN) recommends the recruitment of all males carrying BRCA1 or BRCA2 pathogenetic variants within the same screening programs, especially for breast and prostate cancer." (PMID 35454911, 2022). "It is known that, compared with non-carriers, carriers of germline BRCA1/2 mutations can present with more aggressive disease and have a higher risk of recurrence and prostate cancer-specific mortality." (PMID 35380723, 2022). "BRCA1 inhibited the estradiol-inducible transcriptional activity of ERα in breast and prostate cancer cells whereas cancer-associated BRCA1-mutant cells did not exhibit depressed ERα activity." (PMID 35432218, 2022). "For example, the poly(ADP-ribose) polymerase inhibitor olaparib leads to an improvement in progression-free survival of ~3 years in patients with BRCA1/2-altered ovarian tumors, compared with up to ~7 months for BRCA1/2-altered breast, pancreatic, or prostate cancer." (PMID 35055387, 2022). "Early studies showed that BRCA1 and BRCA2 mutations have an increased risk of prostate cancer." (PMID 36294924, 2022). "In addition, five prostate cancer–associated genes (EGF, PIK3R1, ATM, BRCA1, and BRCA2) with apparent damaging mutations, one of which is a rare mutation in ATM, a possible therapeutic target, further support this claim." (PMID 36643868, 2022).
prostate carcinoma (continued). "PARP inhibitors (PARPi) are current treatment options for patients with ovarian, breast, pancreatic, and prostate cancer harboring mutations in BRCA1 or BRCA2 (BRCAm) but they have also been approved in broader patient populations in ovarian and prostate cancer." (PMID 36969741, 2022). "Splice-disrupt variants on BRCA1, AKR1C3, and KLK3 is observed in all types of prostate cancer." (PMID 35286517, 2022). "Conversely, BRCA1/2 PVs in prostate cancer occur more frequently as a somatic hit." (PMID 35563100, 2022). "In addition, other frequently altered DDR genes in prostate cancer are BRCA1, ATM, CDK12, RAD51C, and FANCD2." (PMID 35205654, 2022). "The risks of developing prostate cancer by the age of 75 years were reportedly 21% and 27% for BRCA1 and BRCA2 GPV carriers, respectively, and the risks of developing pancreatic cancer by 75 years were reportedly 1–3% and 3–5% for BRCA1 and BRCA2 GPV carriers, respectively." (PMID 35806485, 2022). "For BRCA1 carriers, risk for prostate cancer was higher for those with a positive family history of prostate cancer (SIR = 3.2) than for those without (SIR = 2.3)." (PMID 35732815, 2022). "We found this trend in AA prostate cancer, which have higher frequencies of germline BRCA1 VUS." (PMID 36922933, 2022). "The interim analysis of the study has reported that after 3 years of PSA screening in men with germline BRCA1/2 mutations, those with a BRCA2 mutation had increased incidence of prostate cancer, younger age at diagnosis, and higher risk of developing clinically significant tumours." (PMID 36010882, 2022). "The associations of BRCA1/2 PVs with the risks of male breast and pancreatic cancers were confirmed and refined, as well as the association of prostate cancer with BRCA2 PVs, regardless of age and aggressiveness." (PMID 35077220, 2022). "In addition, BRCA1/2 GPV carriers have increased risks of developing prostate cancer, pancreatic cancer, and malignant melanoma." (PMID 35806485, 2022). "In a multinational study of 6500 male patients with BRCA1 and BRCA2 pathogenic sequence variants (PSV), two regions in BRCA2 (c.756-c 1000 and c.7914þ) were identified as high risk for developing Gleason 8b prostate cancer—this was more prominent in PSVs in PCCRs." (PMID 34884434, 2021). "Additionally, the panel’s performance for detecting BRCA1/2 germline mutations, which are predictive biomarkers for PARP inhibitor therapy in breast, ovarian, and prostate cancer, was tested." (PMID 34575676, 2021). "Our study applied a new recommended definition of aggressive prostate cancer and provides further evidence that rare germline pathogenic variants in ATM, BRCA1, and BRCA2 are associated with increased risk of this aggressive, clinically relevant subset of prostate cancer." (PMID 33804961, 2021). "Relatives with germline BRCA1 and BRCA2 mutations could be at increased risk of male breast, colon, pancreatic and prostate cancer." (PMID 34884434, 2021). "Preclinical and limited clinical data suggest that PARP inhibition is effective against prostate cancer (PC) in patients with HRR-deficient tumors and that PARPis can improve the mortality rate of PC in patients with BRCA1/2 mutations through a synthetic lethality." (PMID 34066020, 2021). "EZH2 can also co-regulate prostate cancer stem cell properties with BRCA1." (PMID 33985534, 2021). "While BRCA1/2 germline variants in BRCA, OV, PAAD and prostate cancer are well known to be associated with HRD phenotype, our results identify a much broader range of cancers with different germline alterations in HR-related genes that are significantly associated with HRD." (PMID 34572800, 2021). "Furthermore, PARPi administration to BRCA1/2 mutant cells blocks prostate cancer growth, however, several markers of homologous recombination (HR) signaling are activated, leading to modest clinical outcome." (PMID 34206543, 2021).